MIR1224 (microRNA 1224)
Synonyms: hsa-mir-1224; MIRN1224; mir-1224
Gene: MicroRNA gene on chromosome 3 (184,241,405 to 184,241,489, forward strand). Ensembl gene ENSG00000221120.
Gene Ontology:
Biological process: miRNA-mediated post-transcriptional gene silencing
Homologues: Orthologues: chimpanzee ptr-mir-1224 (100% identical), macaque mml-mir-1224 (95% identical), pig ssc-mir-1224 (93% identical), guinea pig MIR1224 (84% identical), mouse Mir1224 (81% identical).